CASP2 (caspase 2)
Diseases named in the same sentence as CASP2 in open-access papers (continued):
Sharing a sentence is not in itself a finding about the gene and the disease.
liver disease (3 papers, 2022 to 2026). "Relevantly, increased CASP2 levels are associated with liver disease and reduced levels with more favorable prognosis for HCC in patients." (PMID 41477850, 2026). "Proteomic profiling revealed a pathogenic polyploidy–associated signature associated with caspase-2 deficiency and increased predisposition to liver disease and malignancy." (PMID 41477850, 2026). "Future investigations should aim to clarify the cell-autonomous role of caspase-2 and determine whether its activity in hepatocytes or potentially in other liver-resident cell types contributes to the observed phenotypes, including liver disease progression in caspase-2-deficient mice." (PMID 41477850, 2026). "Furthermore, deregulated activation of caspase-2, caspase-3, and caspase-8 contributes to the exacerbation of liver disease injury, while caspase-1, caspase-3, and caspase-6 knockout protect against stroke." (PMID 39625520, 2024). "Mounting evidence has revealed the regulation of caspase-2 by miRNAs in liver diseases." (PMID 36171196, 2022). "Could any other liver-specific miRNAs potentially regulate caspase-2 in the progression of different liver disorders?" (PMID 36171196, 2022). "Thus, we cannot rule out the possibility that caspase-2 exerts distinct regulatory effects on both hepatocyte ploidy and inflammatory pathways, which may synergistically contribute to the initiation and progression of liver disease." (PMID 41477850, 2026).
liver fibrosis (3 papers, 2016 to 2026). "Thus, the elevated inflammatory phenotype in caspase-2-deficient mice is a key driver of liver fibrosis." (PMID 41477850, 2026).
metabolic syndrome (3 papers, 2016 to 2024). A cluster of metabolic risk factors for CARDIOVASCULAR DISEASES and TYPE 2 DIABETES MELLITUS. "Caspase-2-deficient mice fed a high-fat diet are protected from abdominal fat deposition, dyslipidemia, and hepatic steatosis." (PMID 39625520, 2024). "In a mouse model of diet-induced metabolic syndrome, caspase-2 deficiency protects from the development of key aspects of the metabolic syndrome, including central obesity, dyslipidemia, T2DM and NAFLD." (PMID 26890135, 2016). "Recently, caspase-2 was linked to lipoapoptosis, so we hypothesized that caspase-2 might be a critical determinant of metabolic syndrome pathogenesis." (PMID 26890135, 2016). "We hypothesized that caspase-2 may be a key link between energy surplus, adipocyte death and the development of the metabolic syndrome and NAFLD." (PMID 26890135, 2016). "We fed Western diet to WT and caspase-2-deficient mice for 16 weeks, and despite similar food intake, caspase-2-deficient mice gained less weight and fat mass, were more glucose tolerant and insulin sensitive, did not develop dyslipidemia, and were protected from NAFLD." (PMID 26890135, 2016).
optic neuritis (3 papers, 2012 to 2017). Optic neuritis is inflammation of the optic nerve, the nerve that carries the visual signal from the eye to the brain.The conditionmay cause sudden, reduced vision in the affected eye(s). "This suggests that inhibition of caspase-2 activation using a therapeutic siRNA may be a useful approach that could be useful in the treatment of optic neuritis and other inflammatory optic neuropathies in humans." (PMID 24223903, 2013).
optic neuropathies (3 papers, 2012 to 2023). "Codosiran (QPI-1007) inhibits the loss of retinal ganglion cells (RGCs) and prevents optic neuropathy by targeting Caspase-2 (CASP2), which is highly expressed in RGCs during optical injury." (PMID 37430086, 2023). "QPI-1007 inhibits the expression of caspase 2 by targeting caspase 2 mRNA and protects the loss of retinal ganglion cells in optic neuropathies." (PMID 35352626, 2022).
steatosis (3 papers, 2017 to 2026). Increased lipid within the cytoplasm of cells. "We assessed the incidence of age-related steatosis and inflammation in standard laboratory diet–fed caspase-2-deficient mice." (PMID 41477850, 2026).
Stroke (3 papers, 2022 to 2024). Sudden impairment of blood flow to a part of the brain due to occlusion or rupture of an artery to the brain. "Male MMP-3 KO stroke brains also exhibited downregulation of apoptosis-related genes such as Casp9, Casp7, Bmf, Casp1, Bid, Casp6, Casp3, Casp2, Fas, Casp4, and Casp8." (PMID 39000490, 2024).
B-cell lymphoma (2 papers, 2015 to 2019). "Strikingly, Raidd deficiency also had no influence on tumor latency in c-Myc-driven B-cell lymphomas, contrasting the findings with Caspase-2- or Pidd1-deficient mice, where Caspase-2 acts as a tumor suppressor and Pidd1 as a tumor promoter in this model." (PMID 25857265, 2015). "The lack of clinical correlation with Megf6 expression in B-cell lymphoma may be indicative of a tissue-specific function for Megf6 and/or that Casp2 loss can cooperate with high Megf6 expression to augment lymphomagenesis in the EμMyc/Casp2−/− model." (PMID 30670683, 2019).
cognitive decline (2 papers, 2023 to 2024). "We do know that overexpression of caspase-1, caspase-2, caspase-3, caspase-6, and caspase-8 is linked to Aβ accumulation and cognitive decline in mouse models and patients with neurodegenerative diseases." (PMID 39625520, 2024). "In this respect, it is interesting that a decrease in CASP2 expression in the brain reverses memory deficits in one model for Alzheimer's‐like disease, and caspase is also required for the cognitive decline observed in another model for the same disease." (PMID 37646198, 2023).
frontotemporal dementia (2 papers, 2019). Frontotemporal dementia (FTD) comprises a group of neurodegenerative disorders, characterized by progressive changes in behavior, executive dysfunction and language impairment, as a result of degeneration of the medial prefrontal and frontoinsular cortices. "Rendering tau resistant to Casp2 cleavage preserves memory function, and lowering Casp2 restores memory function in mice expressing mutant human tau linked to frontotemporal dementia." (PMID 31362787, 2019).
glaucoma (2 papers, 2012 to 2025). Increased pressure in the eyeball due to obstruction of the outflow of aqueous humor. "This study presents an innovative dual-delivery approach for glaucoma management using Spanlastic nanovesicles, with timolol maleate and Caspase-2 siRNA encapsulated in separate but complementary formulations." (PMID 40681573, 2025). "Collectively, these findings highlight the promise of a dual-spanlastic-based delivery platform as a safe, non-invasive, and effective therapeutic strategy for glaucoma, combining IOP-lowering efficacy with targeted caspase-2 silencing in RGC." (PMID 40681573, 2025).
Glucose intolerance (2 papers, 2015 to 2016). Glucose intolerance (GI) can be defined as dysglycemia that comprises both prediabetes and diabetes. "Increased fasting blood glucose and impaired glucose tolerance are normally associated with ageing, thus these results suggest that Casp2−/− mice show resistance to age-induced glucose intolerance." (PMID 25611376, 2015).
hyperlipidaemia (2 papers, 2017 to 2022). "Casp2 inhibition reduces hepatosteatosis and steatohepatitis, inflammation, and liver damage, and it prevents cholesterol accumulation and hyperlipidemia, suggesting that Casp2 is an interesting target for the prevention or treatment of NASH." (PMID 36379916, 2022).
ischemia (2 papers, 2012 to 2022). A hypoperfusion of the BLOOD through an organ or tissue caused by a PATHOLOGIC CONSTRICTION or obstruction of its BLOOD VESSELS, or an absence of BLOOD CIRCULATION. "In addition, caspase-2 deficient neurons are resistant to apoptosis induced by β-amyloid, while activation of caspase-2 occurs in hippocampal neurons after transient global ischemia." (PMID 23285297, 2012). "Furthermore, it was verified that the administration of broad-spectrum inhibitor targeting pro-apoptotic factors, including caspase-2, caspase-3 and caspase-7, at initial time of reperfusion could lead to shrunken size of post-ischemia infarct." (PMID 35475469, 2022).
Lewy body dementia (2 papers, 2019 to 2022). A progressive form of dementia characterized by the presence of protein deposits called Lewy bodies in the midbrain and cerebral cortex, and loss of cholinergic and dopaminergic neurons. "Studies from our laboratory have also implicated caspase-2 in Lewy Body Dementia (LBD)." (PMID 36129947, 2022).
Miscarriage (2 papers, 2024). A pregnancy that ends at a stage in which the fetus is incapable of surviving on its own, defined as the spontaneous loss of a fetus before the 22th week of pregnancy. "Exposure to PS-NPs triggered the activation of Bcl-2/Cleaved-caspase-2/Cleaved-caspase-3, resulting in excessive apoptosis in the mice’s placental tissues and subsequently inducing miscarriage." (PMID 39195655, 2024).
multiple myeloma (2 papers, 2014 to 2022). "Our results showed high caspase 2 activity after treatment with new highly genotoxic analogs, mainly in multiple myeloma cells, which indicated high genomic instability." (PMID 36430734, 2022). "Our study on caspase 2 activation in multiple myeloma cells and leukemic cells showed a significant increase in caspase activity, mainly after 24 h incubation." (PMID 36430734, 2022). "It has also been documented that a relationship exists between ER stress and caspase-2 activation in human multiple myeloma cells." (PMID 25226616, 2014).
oral cancer (2 papers, 2015 to 2023). "In oral cancer CAL 27 cells, GSE also reported to induce mRNA overexpression of apoptosis-associated signaling such as caspase-2 and caspase-8." (PMID 25880412, 2015).
retinal degeneration (2 papers, 2008 to 2022). Degeneration of the retina. "Severe retinal degeneration was observed in the transgenic mice after intense light exposure and a number of genes including CASP2 were identified as potential targets of this cluster." (PMID 36171196, 2022). "Moreover, the inhibition of caspase-2 with Z-VDVAD-FMK partially rescued the retinal damage induced by the acute light exposure, indicating that the miR-183/96/182 cluster prevents light-induced retinal degeneration by mediating caspase-2 expression." (PMID 36171196, 2022). "Increased levels of caspase 2 are important in cell death activated by DNA damage, and we found this gene to be downregulated by both injuries, which suggests that DNA damage is not the main pathway for the optic nerve injury-induced retinal degeneration." (PMID 18552980, 2008).
viral infection (2 papers, 2023 to 2024). "CD4 T cells express all three classes of caspases and the transcriptions of caspase 2 and 10 (initiator), caspase 1 (inflammatory), and caspase 3 and 7 (executioner) were upregulated during the viral infection." (PMID 36780482, 2023).
acquired immune deficiency syndrome (1 paper, 2022). "In contrast, the death of Vγ2Vδ2 T cells was highly dependent on the p38-caspase-2, -8, and -9 signaling pathways during progression to acquired immune deficiency syndrome (AIDS)." (PMID 35619176, 2022).
adult T-cell leukemia/lymphoma (1 paper, 2020). A peripheral (mature) T-cell neoplasm linked to the human T-cell leukemia virus type 1 (HTLV-1), adult T-cell leukemia/lymphoma is endemic in several regions of the world, in particular Japan, the Caribbean, and parts of Central Africa. "Recently, a novel RAIDD-caspase-2-mediated intrinsic cell death pathway was reported in adult T-cell leukemia/lymphoma (ATLL) following treatment with an inhibitor of deacetylase enzymes (LBH589), an anticancer drug, both in vitro and in vivo." (PMID 32438737, 2020).
anterior ischemic optic neuropathy (1 paper, 2019). Anterior ischemic optic neuropathy (AION) is an eye disease characterized by infarction of the optic disk leading to vision loss. "Intraocular QPI-1007, an experimental siRNA against Casp2 used to treat non-arteritic anterior ischemic optic neuropathy, has thus far shown no serious harmful effects in clinical trials." (PMID 31362787, 2019).
Anxiety (1 paper, 2019). Intense feelings of nervousness, tension, or panic often arise in response to interpersonal stresses. "We performed a battery of behavioral tests to examine anxiety and memory in Casp2 KO mice and their WT littermates." (PMID 31399584, 2019). "Our analysis of cultured neurons and mice reveals that caspase-2 deficiency leads to deficits in internalization of AMPARs, impaired LTD expression, reduced spine pruning, elevated anxiety, enhanced memory, and cognitive inflexibility." (PMID 31399584, 2019). "Furthermore, we found that mice lacking caspase-2 displayed elevated levels of anxiety, impairment in reversal water maze learning, and little memory loss over time." (PMID 31399584, 2019).
astrocytoma (1 paper, 2022). "In the astrocytoma cell line, we found that the gene encoding Caspase 2 was upregulated in relation to HDFa control (3.15)." (PMID 36142793, 2022).
autoimmune encephalitis (1 paper, 2026). Inflammation of the brain secondary to an immune response triggered by the body itself. "Another mechanism may be potassium or calcium dysregulation, especially in the cases of autoimmune encephalitis associated with NMDA, LGI1, Casp2, AMPAR, or DPPX antibodies." (PMID 41598359, 2026).
Babesia infection (1 paper, 2020). "We also analyzed porin functions in relation to both tick blood feeding and Babesia infection and the relationship between porin and porin-related apoptosis genes such as B-cell lymphoma (Bcl), cytochrome complex (Cytc), caspase 2 (Cas2), and caspase 8 (Cas8)." (PMID 32508681, 2020).
Brain atrophy (1 paper, 2011). Partial or complete wasting (loss) of brain tissue that was once present. "Casp2-/- mice are not protected from pathological signs of HD including testicular atrophy and regionally specific brain atrophy as assayed by stereology and magnetic resonance imaging techniques." (PMID 21854568, 2011).
brain injury (1 paper, 2022). Acute and chronic (see also brain INJURIES, CHRONIC) injuries to the brain, including the cerebral hemispheres, CEREBELLUM, and brain STEM. "Previous studies have shown that miR-150-3p enhances neuroprotective effects of neural stem cell exosomes after hypoxic-ischemic brain injury by targeting CASP2." (PMID 36497037, 2022).
brucellosis (1 paper, 2013). Brucellosis is a bacterial infection that spreads from animals to people via unpasteurized dairy products or by exposure to contaminated animal products or infected animals. "Further understanding of caspase-2-mediated pyroptosis can aid in supplying a blueprint for effective brucellosis vaccines (both animals and humans) as well as effective therapeutics against cancers and other diseases." (PMID 24350060, 2013).
Chagas disease (1 paper, 2021). A parasitic infection caused by Trypanosoma cruzi. "We identified the candidate genes and pathways related to Chagas disease for resisting T. cruzi, it is found that CASP2, CASP8, NOD1, MYD88, TLRs, IL-1s, NAIPs, etc, would be responsible for the T. cruzi infection." (PMID 34171992, 2021). "According to these known information, DEGs (CASP2, CASP8, NOD1, MYD88, TLRs, IL-1s, NAIPs) involved in Chagas disease here are screened, which have been proven to be correlated with the activation or inhibition of multiple Chagas disease related pathways." (PMID 34171992, 2021).
cholesteatoma (1 paper, 2015). A pathologic process characterized by the proliferation of keratinizing squamous epithelium resulting in the accumulation of keratin and cells in the middle ear and/or mastoid. "NOD1 and many proapoptotic caspase genes such as CASP1, CASP2, CASP8, and CASP9 were not altered in cholesteatoma." (PMID 25922834, 2015).
chordoma (1 paper, 2023). Chordomas are rare malignant tumors arising from embryonic remnants of the notochord in axial skeleton. "Genes central for module 2 (and thus probably important for functioning of chordomas in both clusters) were either responsible for cell division and DNA repair process (e.g. ATM, CHEK, BMI1, MDM2) or parts of inhibitors of apoptosis cascade (e.g. CASP2, CASP8, SIRT2)." (PMID 37434245, 2023).
co-infection (1 paper, 2015). "qRT-PCR also demonstrated co-infection significantly increased expressions of CASP2, CASP3, BC2L11, FASLG, and TNFRSF8." (PMID 25906258, 2015).
Hepatitis (1 paper, 2026). Inflammation of the liver. "In addition to early hyperpolyploidy, the increase in infiltrating immune cells and severity of inflammation by 12 months of age in Casp2C320S livers is a significant feature of early liver damage and hepatitis-driven liver injury in caspase-2-deficient mice." (PMID 41477850, 2026). "Our findings underscore the significance of caspase-2 enzymatic function in maintaining age-related liver homeostasis and protecting against hepatitis-induced liver pathology and HCC." (PMID 41477850, 2026). "Our data also suggest that chronic liver inflammation and disease in 12-month-old caspase-2-deficient mice are partly independent of MASLD." (PMID 41477850, 2026).
Hepatomegaly (1 paper, 2016). Abnormally increased size of the liver. "Hepatomegaly in WT mice was due to a 5–6-fold increase in liver fat content (as assessed by DXA and triglyceride measurement), whereas caspase-2-deficient mice had strikingly lower hepatic fat accumulation and were protected from Western diet-induced hepatomegaly." (PMID 26890135, 2016).
Hydrocephalus (1 paper, 2024). Hydrocephalus is an active distension of the ventricular system of the brain resulting from inadequate passage of CSF from its point of production within the cerebral ventricles to its point of absorption into the systemic circulation. "So, we conclude that optic atrophy in Family 5, individual II-1 may be due more to secondary to hydrocephalus rather than having truncating CASP2 variants." (PMID 37880421, 2024).
latent infection (1 paper, 2015). "For example, a decrease in caspase-2, a proapoptotic miR-708-5p target, would benefit maintenance of KSHV latent infection." (PMID 25942495, 2015).
lung squamous cell carcinoma (1 paper, 2020). "Interestingly, the Serine conserved position that corresponds to the Ser-384 residue in caspase-2 is also subjected to missense mutagenesis in caspase-5 and -6 in lung squamous cell carcinoma and adenocarcinoma." (PMID 33011746, 2020).
malaria (1 paper, 2015). Malaria is a serious and sometimes fatal disease caused by a parasite that commonly infects a certain type of mosquito which feeds on humans.
malignant glioma (1 paper, 2016). A grade III or grade IV glioma arising from the central nervous system. "In contrast, caspase-2 is constitutively expressed in most human malignant glioma cell lines." (PMID 27049919, 2016).
megalencephaly (1 paper, 2023). A congenital abnormality in which the occipitofrontal circumference is greater than two standard deviations above the mean for a given age. "The Arg170Cys mutation abolishes CRADD’s ability to activate caspase-2, resulting in reduced neuronal apoptosis, leading to megalencephaly." (PMID 36859317, 2023).
ovarian dysfunction (1 paper, 2026). The inability of the ovaries to function. "Reduced CASP2 activity may also disrupt cell cycle regulation and DNA repair, exacerbating ovarian dysfunction." (PMID 41490440, 2026).